AVP (arginine vasopressin)
Diseases named in the same sentence as AVP in open-access papers (continued):
Sharing a sentence is not in itself a finding about the gene and the disease.
Hyponatremia (continued). "The pro-inflammatory cytokine IL-6, which is able to induce AVP release by central and peripheral mechanisms, may represent the common denominator of acute respiratory insufficiency and hyponatremia secondary to SIAD." (PMID 36831539, 2023). "The increased production of AVP and salt and water retention in the proximal and distal tubules of the kidney by humoral, hemodynamic, and neural mechanisms increase circulatory blood volume and contribute to hyponatremia." (PMID 36836016, 2023). "Moreover, patients with heart failure had higher plasma AVP levels and hyponatremia with electrocardiographic evidence of an increased QRS interval on admission compared with those without heart failure." (PMID 36836016, 2023). "Therefore, the water retention and hyponatremia occurred by active renin-angiotensin-aldosterone system and arginine-vasopressin system." (PMID 36830256, 2023). "Elevated AVP levels in hyponatremia could potentially affect osteoblast function through its receptors." (PMID 37992803, 2023). "A 24–48h run-in period prior to randomisation will allow exclusion of patients with autocorrection of hyponatraemia due to an acutely reversible cause of non-osmotic AVP release." (PMID 35449020, 2022). "Emesis and hyponatremia may well be interconnected, considering the pathophysiological interplay of emesis, hypovolemia, and arginine vasopressin release." (PMID 35745553, 2022). "High levels of AVP results in hyponatremia and inflammatory disorder." (PMID 35328489, 2022). "However, CSW syndrome, initially hypovolemic, can successively develop euvolemia; this is due to compensatory mechanisms of AVP release secondary to hypovolemia, despite hyponatremia, because the hypovolemic stimulus is more life-saving." (PMID 34468821, 2022). "It rarely induces hyponatremia via increasing plasma AVP levels." (PMID 36233678, 2022). "A sustained AVP-dependent antidiuresis in CHF prompts chronic water retention exceeding the RAAS-induced renal natrium reabsorption with a subsequent dilutional (hypervolemic) hyponatremia." (PMID 34713389, 2022). "Hypovolemia is the main stimulus for ADH/AVP secretion, even in the presence of reduced serum osmolarity when hyponatremia may evolve." (PMID 36187132, 2022). "Natriuresis is followed by volume depletion, secondary AVP increase, and hyponatremia." (PMID 34468821, 2022). "Both hypovolemia and severe inflammation could result in the activation of arginine-vasopressin (AVP) production resulting in water retention and hyponatremia." (PMID 34935083, 2022). "Recent studies show that proinflammatory cytokines may regulate AVP secretion and the development of hyponatremia." (PMID 34935083, 2022). "AVP secretion occurs despite hyponatremia, following baroreceptor stimulation." (PMID 34468821, 2022). "Patients with hyponatremia states were characterized by inappropriately elevated plasma AVP levels." (PMID 36157210, 2022). "Nevertheless, the 3-day lag time between the elevation of OXT on D4 and the hyponatremia on D7 could be explained by the respective mechanisms of action of AVP and OXT leading to the excretion of water and sodium." (PMID 33506439, 2021). "We therefore hypothesized that the supplementary activation of the apelin-R by a metabolically stable K17F analog could counteract AVP-induced water reabsorption and correct hyponatremia." (PMID 33436646, 2021). "We therefore hypothesized that activating the apelin receptor (apelin-R) with LIT01-196, a metabolically stable apelin-17 analog, may be beneficial for treating the Syndrome of Inappropriate Antidiuresis, in which AVP hypersecretion leads to hyponatremia." (PMID 33436646, 2021). "Infection can cause excess release of proinflammatory cytokines, such as interleukin-1β and interleukin-6 (IL-6), which induce nonosmotic release of arginine vasopressin, causing hyponatremia due to SIAD." (PMID 33624101, 2021).
Hyponatremia (continued). "Previous in vitro and in vivo studies have shown that chlorpropamide, once thought to cause the SIADH, can cause hyponatremia by inducing the V2R-mediated pathway in the absence of AVP." (PMID 34955900, 2021). "This has led to hypothesize that activation of the ApelinR with an ApelinR agonist might counteract AVP-induced water reabsorption, thereby correcting hyponatremia." (PMID 34880830, 2021). "The administration of LIT01-196 (900 nmol/kg, s.c.) for two days in this rat model of hyponatremia, by re-establishing the “AVP/(apelin + LIT01-196)” balance, inhibited the effects of AVP on urine output and urine osmolality effectively, and induced a progressive correction of plasma sodium levels." (PMID 34880830, 2021). "Hyponatremia (serum sodium < 130 mEq/L; low serum osmolality) is a potentially fatal complication associated with MDMA use and results from increased AVP secretion caused by the MDMA metabolite HMMA." (PMID 34554408, 2021). "Overdrinking and non-osmotic arginine vasopressin release are the main risk factors for exercise-associated hyponatremia (EAH) in ultra-marathon events." (PMID 34867470, 2021). "It is well known that hyponatremia and malignancy are closely related, and several factors were suggested as contributors to hyponatremia, including antineoplastic therapy, adrenal metastasis, and arginine vasopressin." (PMID 32616002, 2020). "High serum levels of arginine vasopressin (also known as antidiuretic hormone (ADH)) should be considered as a prerequisite for the development and maintenance of hyponatremia in view of the fundamental role of the suppression of ADH secretion for the renal excretion of any water load." (PMID 33228240, 2020). "Sodium losses are compounded by increased arginine vasopressin secretion and a relative increase in total body water, which may lead to hyponatremia." (PMID 33104204, 2020). "On the flip side, an inappropriate release of AVP may lead to a dilutional hyponatremia and to a deleterious outcome in CHF." (PMID 32912147, 2020). "All these drugs have been linked to hyponatremia from non-osmotic AVP secretion, but their relationship to polydipsia is under-appreciated." (PMID 31284689, 2019). "MDMA-induced hyponatremia is hypothesized to result from enhanced serotonergic activity and arginine vasopressin (AVP) release in the brain leading to hyperthermia-induced polydipsia and syndrome of inappropriate antidiuretic hormone (SIADH) secretion." (PMID 29270322, 2017). "Namely, inappropriate secretion of AVP is in concert with pathological states of hyponatremia." (PMID 29088071, 2017). "Evidence suggests that the osmotic set point for AVP secretion may be lower in patients with polydipsia and hyponatraemia, leading to impairment in water excretion." (PMID 25688318, 2015). "This suggests that IL-6 stimulates AVP-secreting neurons, increasing the serum levels of AVP which may lead to the development of hyponatremia." (PMID 25853137, 2015). "On the contrary, decrease of effective osmolality (hypoosmotic hyponatremia) decreases AVP release." (PMID 26553121, 2015). "First of all, it should be kept in mind that hypovolemia, irrespective of its cause, is a powerful inductor of AVP release so that any concomitant input of hypotonic fluids is bound to generate hyponatremia." (PMID 26553121, 2015). "Persistent secretion of AVP contributes to the hyponatremia." (PMID 25853137, 2015). "Thus, although BNP was elevated in almost all patients with SAH, AVP was selectively elevated in those with hyponatremia, supporting the authors’ clinical impression that the majority of patients had hyponatremia due to SIADH." (PMID 26237593, 2014). "This further supports the role of AVP in hyponatremia in pregnancy." (PMID 24803942, 2014). "The main pathogenic factor responsible for hyponatraemia is a non-osmotic hypersecretion of arginine vasopressin (AVP) or antidiuretic hormone from the neurohypophysis, related to circulatory dysfunction." (PMID 24760233, 2014).
Hyponatremia (continued). "In each patient who developed hyponatremia, AVP was significantly higher before and during the episode of hyponatremia compared with AVP levels measured once the hyponatremia had resolved, consistent with the majority of cases of hyponatremia being due to SIADH." (PMID 26237593, 2014). "Impaired renal sodium handling due to renal hypoperfusion and increased arginine-vasopressin secretion secondary to reduced effective volemia due to peripheral arterial vasodilation represent the main mechanisms leading to dilutional hyponatremia in this setting." (PMID 26237020, 2014). "The results of the small urine substudy suggest that appropriate and inappropriate AVP secretion may both occur in the pathophysiology of hyponatraemia in imported malaria." (PMID 22280539, 2012). "Thus, increased urinary AQP2 excretion, in the setting of euvolemic hyponatremia and low or undetectable levels of serum AVP, suggests the possibility of NSIAD." (PMID 22325688, 2012). "Indeed, one of the children had two episodes of seizures related to hyponatremia with low plasma AVP level, when he was 10 months and 34 months." (PMID 22518188, 2012). "In the pathophysiology of hyponatraemia in malaria, the relative contribution of appropriate and inappropriate arginine vasopressin (AVP) release is unknown; the trigger for inappropriate AVP release is also unknown." (PMID 22280539, 2012). "Most patients appeared to have a relatively clear phenotype with biological features initially suggesting a syndrome of inappropriate antidiuretic hormone secretion (SIADH) with hyponatremia, low serum osmolality, and unexpectedly high urine osmolality, but low plasma AVP levels." (PMID 22518188, 2012). "Since the basic pathophysiology of water retention and dilutional hyponatremia in cirrhotics is antidiuretic hormone or arginine vasopressin (AVP) induced water resorption from the distal collecting duct, it would appear logical to block this action of AVP and inhibit the pure water resorption." (PMID 21994871, 2011). "Therefore, this study indicated that the administration of isotonic fluids, namely saline and balanced crystalloids, could prevent the development of hyponatremia, despite the common occurrence of an elevation in AVP concentrations after a kidney biopsy." (PMID 39585356, 2025). "Direct stimulation of AVP release in CNS might also be a mechanism of hyponatremia." (PMID 40886330, 2025). "Following these findings, a recent study investigated whether empagliflozin improves hyponatremia through affecting apelin and AVP, two neuropeptides which regulate water homeostasis in opposing ways; AVP by promoting antidiuresis, whereas apelin by augmenting diuresis." (PMID 39435353, 2024). "The choice of SCLC was based on the fact that, although tumors from different organs and tissues may ectopically secrete AVP and cause SIAD, SCLC is the tumor where the probability that patients experience at least one episode of hyponatremia is highest (>75%)." (PMID 39125971, 2024). "Excess AVP secretion in response to osmotic and non-osmotic stimuli will cause stimulation of AVP V2 receptors, which leads to free water retention resulting in hyponatremia in congestive heart failure (CHF)." (PMID 37508636, 2023). "Additionally, cisplatin stimulates AVP secretion; however, it may also directly damage the renal tubules’ interference with sodium reabsorption, which may result in hyponatremia." (PMID 36676789, 2023). "The incidence of hyponatremia due to SIADH is also high in Cushing's disease patients as a post-surgical osmoregulatory complication, essentially central adrenal insufficiency, whereby glucocorticoid deficiency prompts the compensatory rise of arginine vasopressin (AVP)." (PMID 37700952, 2023).
Hyponatremia (continued). "The pathophysiology of hyponatremia in patients with heart failure is complex, including numerous mechanisms: increased activity of the sympathetic nervous system and the renin–angiotensin–aldosterone system, high levels of arginine vasopressin and diuretic use." (PMID 36675801, 2023). "These could be due to AVP-induced water retention and dilutional hyponatremia and hypokalemia." (PMID 35350852, 2022). "Therefore, the increased release of antidiuretic hormone, also called arginine vasopressin, in patients with SIADH-related hyponatremia may be one of the causes leading to the procoagulant state observed in COVID-19." (PMID 36014944, 2022). "Furthermore, it appears that prominent release of AVP in response to strenous exercise may lead to exercise-induced hyponatremia." (PMID 34867449, 2021). "Copeptin was negatively associated with serum sodium concentration, indicating an inadequate activation of AVP in ACLD similar to the syndrome of inappropriate antidiuretic hormone secretion (SIADH), causing additional water retention and worsening of dilutional hyponatremia." (PMID 34021479, 2021). "Though it is not common in DDI patients, acute illness associated with AVP stimulating stress may induce hyponatremia." (PMID 33916272, 2021). "In addition, AVP-induced water retention affects hyponatremia." (PMID 34070416, 2021). "In HF, hyponatremia is a product of several simultaneous pathophysiological mechanisms, including arterial underfilling, activation of the sympathetic nervous system and renin-angiotensin-aldosterone system, enhanced arginine vasopressin secretion, renal impairment and diuretic therapy." (PMID 32746925, 2020). "Malignancy-associated hyponatremia may result as a consequence of poor diet, adrenal dysfunction, renal or cerebral salt wasting, and SIADH secretion, via ectopic arginine vasopressin (AVP) production or chemotherapy-induced stimulation of AVP." (PMID 31221202, 2019). "Because excessive AVP release is the key etiologic factor in perpetuating the hyponatremia observed in patients with common clinical conditions such as CHF, cirrhosis, nephrosis, and SIADH, therapy that directly antagonizes AVP receptors potentially may offer better outcomes." (PMID 24558627, 2013). "Furthermore, during the water loading challenge, serum AVP levels decreased from a baseline of 2.6 pg/mL to 1.1 pg/mL, the approximate assay limit of detectability, by one hour, when the patient had developed hyponatremia and serum hypoosmolality." (PMID 22325688, 2012). "Hyponatremia may result from several factors related to cirrhosis and portal hypertension, the most prominent of which is increased release of arginine vasopressin (AVP; also known as antidiuretic hormone, or ADH)." (PMID 22732834, 2012). "Thus, the hyponatremia of adrenal insufficiency is dependent on elevated AVP release." (PMID 22934055, 2012). "However, the exact mechanisms by which SARS‐CoV‐2 may cause neurological manifestations, including direct neuropathic effects, AVP/ADH‐induced hyponatremia, or excessive inflammatory responses triggered by cytokine release from the host immune system, remain to be determined." (PMID 40437871, 2025). "Regarding the relationship between serum sodium concentrations and PONV and pain, a previous report showed that all patients who developed hyponatremia showed PONV and pain and elevated AVP concentrations." (PMID 39585356, 2025). "In addition to iatrogenic hyponatraemia, it is postulated that surgical insult may have also led to an increased production of endogenous AVP from the supra-optic and paraventricular nucleus of the hypothalamus, which further precipitates hyponatraemia in the setting of partial AVP-D." (PMID 38657650, 2024). "Experiments on HF rats have revealed that GC, through the inhibition of the arginine vasopressin (AVP) pathway, can counter dilutional hyponatremia." (PMID 38026943, 2023).
Hyponatremia (continued). "A proper space will be dedicated to the only specific class of drugs approved for the treatment of hyponatremia secondary to SIAD, so far, namely vaptans, which are arginine vasopressin (AVP) and receptor (AVPR) antagonist." (PMID 36831539, 2023). "Most hyponatremia cases are due to the syndrome of inappropriate antidiuretic hormone secretion (SIAD), which is characterized by high arginine vasopressin (AVP) levels." (PMID 37992803, 2023). "In our target population, i.e., the geriatric patients scheduled for digestive tract surgery, two additional predisposing factors for hyponatremia might be the increased nonosmotic AVP secretion (stimulated by the volume depletion) and the reduced oral sodium intake." (PMID 34558033, 2022). "In a rat experimental model of AVP-induced hyponatremia, LIT01-196 subcutaneously administered blocks the antidiuretic effect of AVP and the AVP-induced increase in urinary osmolality and induces a progressive improvement of hyponatremia." (PMID 33436646, 2021). "The mechanism of anticonvulsant-associate hyponatremia has generally been considered to be inappropriate hypersecretion of AVP, but an experimental study has indicated a direct effect of carbamazepine on the kidney through V2R stimulation without evidence of increased release of endogenous AVP." (PMID 34955900, 2021). "Another factor contributing to impaired excretion of excess water is dissociation of arginine vasopressin (AVP) release from osmoregulation, a situation brought about by disorders and drugs that result in water retention, hyponatremia, and edema." (PMID 34268347, 2021). "In most patients, hyponatraemia is either euvolaemic due to SIADH, mainly owing to IL-6-induced AVP release, or hypovolaemic due to significant insensible fluid loss." (PMID 34370712, 2021). "As traditional treatments for hyponatremia are difficult for patients to tolerate, have marginal efficacy, and could result in electrolyte imbalances, vasopressin antagonists were developed specifically to counteract the abnormal pathophysiology resulting from an excess of AVP." (PMID 32996719, 2020). "In athletes who may have a large amount of fluid in the stomach (from recent ingestion) and have elevated AVP levels, rapid absorption of this fluid (as gastrointestinal blood flow post-event increases) along with impaired free water excretion may set up athletes to develop hyponatremia." (PMID 28316971, 2017). "Taken together, these data might suggest that activation of the AVP system - measured by copeptin levels - is not the primary cause of volume overload and hyponatremia among patients with right heart strain, but might reflect an early indication of neurohumoral stimulation." (PMID 24251953, 2013). "Concerning the plasma AVP levels measured in these NSIAD patients, most levels appeared to be low or undetectable in spite of hyponatremia and high urine osmolality." (PMID 22518188, 2012). "In contrast, in chronic groups, no increased brain water content was observed neither in AVP- (p = 0.053, n = 6) nor dDAVP-induced hyponatremia (p = 0.068, n = 6 vs. Sham group, n = 6)." (PMID 40603486, 2025). "Among patients with elevated AVP concentrations, 60% of those who received hypotonic fluids developed hyponatremia, while no hyponatremia was observed in patients who received isotonic fluids." (PMID 39585356, 2025). "In the current study, AVP concentrations were increased in 24% of patients, which is a similar rate to our previous study, but no cases of hyponatremia were observed." (PMID 39585356, 2025). "In this study, copeptin was associated with the primary end point, indicating harmful activation of the AVP system even in the absence of overt hyponatremia." (PMID 40317183, 2025). "The main mechanism is renal sodium loss, which reduces effective circulating volume and triggers baroreceptor-mediated non-osmotic AVP secretion, leading to hypovolemic hyponatremia." (PMID 41010788, 2025).